RAB40A (RAB40A, member RAS oncogene family)
Description:
RAB40A small GTPase acts as substrate-recognition component of the ECS(RAB40A) E3 ubiquitin ligase complex which mediates the ubiquitination and subsequent proteasomal degradation of target proteins. The Rab40 subfamily belongs to the Rab family that are key regulators of intracellular membrane trafficking, from the formation of transport vesicles to their fusion with membranes. Rabs cycle between an inactive GDP-bound form and an active GTP-bound form that is able to recruit to membranes different sets of downstream effectors directly responsible for vesicle formation, movement, tethering and fusion (By similarity). As part of the ECS(RAB40A) complex, mediates RHOU 'Lys-48'-linked ubiquitination and degradation, thus inhibiting focal adhesion disassembly during cell migration.
Synonyms: RAR2A; Rar-2; RAR2
Tractability: Antibody: UniProt places it where antibodies can reach, with high confidence; its Gene Ontology location is reachable by antibodies, with medium confidence. PROTAC: ubiquitination databases record sites on it.
Gene: Protein-coding gene on chromosome X (103,496,541 to 103,526,752, reverse strand). Ensembl gene ENSG00000172476.
Subcellular location: Cell membrane
Subcellular location (Human Protein Atlas): Vesicles
Pathways (Reactome):
Metabolism of proteins: RAB geranylgeranylation
Gene Ontology:
Molecular function: ubiquitin-like ligase-substrate adaptor activity; GTPase activity; G protein activity; GTP binding
Biological process: negative regulation of focal adhesion disassembly; proteasome-mediated ubiquitin-dependent protein catabolic process; exocytosis; intracellular signal transduction; protein ubiquitination
Cellular component: Cul5-RING ubiquitin ligase complex; Golgi apparatus; lipid droplet; endosome; plasma membrane; synaptic vesicle
Homologues: Orthologues: macaque RAB40A (95% identical). Paralogues in human: RAB40AL (98% identical), RAB40B (88% identical), RAB40C (76% identical), RAB10 (28% identical), RAB1A (27% identical), RAB1B (27% identical), RAB8A (27% identical), RAB15 (27% identical), RAB6A (27% identical), RAB13 (27% identical), RAB8B (27% identical), RAB6B (26% identical), and 56 more.
Diseases named in the same sentence as RAB40A in open-access papers:
RAB40A is named in the same sentence as 6 diseases in open-access papers, as found by Europe PMC text mining. Sharing a sentence is not in itself a finding about the gene and the disease. The quoted sentences say what the papers report.
autism (1 paper, 2020). Persistent deficits in social interaction and communication and interaction as well as a markedly restricted repertoire of activity and interest as well as repetitive patterns of behavior. "Also, a small 252-kb duplication spanning BEX3, TCEAL4, TCEAL9, and RAB40A has been reported in a patient with autism (Decipher database, ID: 290829)." (PMID 33100228, 2020).
breast carcinoma (1 paper, 2016). "Rab40b is upregulated in grade 3 breast cancers, but its close homologues Rab40a and Rab40c are not." (PMID 27789576, 2016).
lung carcinoma (1 paper, 2025). "However, it is interesting to note that RAB40AL, a closely related isoform of RAB40A, is linked to Martin-Probst Syndrome and lung cancer cell migration." (PMID 39736966, 2025).
stomach cancer (1 paper, 2025). "Despite its role in cell migration, we could not find direct evidence of RAB40A in stomach cancer metastasis." (PMID 39736966, 2025).
RAB40A also shares sentences with these, for which no sentence is quoted: cancer (1 paper); infection (1).